EPHA2 (EPH receptor A2)
Diseases named in the same sentence as EPHA2 in open-access papers (continued):
Sharing a sentence is not in itself a finding about the gene and the disease.
tumor (continued). "Xenograft experiments supported the effect of TEM8 overexpression on increasing EphA2 expression, dextran leakage, pericyte density, and tumor vessel density, whereas TEM8 knockdown decreased tumor vessel density." (PMID 34285210, 2021). "Here we showed that the level of EphA2 expression in CC cell lines was positively correlated with tumour cell proliferation, migration and invasion abilities, which was demonstrated by in vivo and in vitro experiments." (PMID 33586348, 2021). "Our study reveals that EphA2 functions in tumors to promote osteolysis of the bone via osteoclast differentiation, at least in part through regulation of IL‐6 production in tumor cells." (PMID 33869989, 2021). "The receptor tyrosine kinase EPHA2 overexpression has been found in the basal-like molecular subtype of BC and has been proposed to promote tumor invasiveness in TNBC and correlate with poor recurrence-free survival (RFS) in TNBC." (PMID 33842315, 2021). "Our results also show that oHSV-based Epha2 expression recruits immune cells to the tumor similar to the parent virus but that the antigen-expressing virus induces antigen-specific immune cells (CD8 T cells) that target the expressed tumor antigens." (PMID 34599026, 2021). "Subsequent xenograft animal model revealed that EphA2-SE deletion suppressed tumor proliferation and survival in vivo." (PMID 33712565, 2021). "In terms of in vivo efficacy, a reduced tumour burden was observed in two immunodeficient xenograft models: intracranial EphA2-positive U373 cells and IV EphA2-positive A549 cells." (PMID 34885108, 2021). "Together, these results suggested that EphA2 was recognized by cytotoxic Vδ1 T cells in the tumor killing." (PMID 34691070, 2021). "Our studies revealed differences in cytokine production by cultured tumor cells (both human and murine) when EphA2 activity is inhibited." (PMID 33869989, 2021). "We also describe the correspondence among primary tumor tissues and patient-derived xenograft (PDXs) models, focusing on EphA2 expression." (PMID 34831119, 2021). "MEDI-547 also induced the degradation of EphA2, effectively inhibited the diffusion of tumor (the inhibition rate was about 85%) and diminished the metastasis rate of tumors." (PMID 34202685, 2021). "EPHA2 is a member of the ephrin receptor tyrosine kinase family and is closely related to the malignant tumor progression." (PMID 33834064, 2021). "Despite these results, given the overexpression of EphA2 in many tumor types targeting EphA2 for toxin delivery remains a promising therapeutic strategy." (PMID 34926242, 2021). "We found that the expression of EphA2 was significantly related to tumor invasion and metastasis in our previous article." (PMID 33941853, 2021). "Markosyan and coworkers demonstrated in mice that tumor cell-intrinsic EPHA2 suppresses anti-tumor immunity by regulating PTGS2 (COX-2) in pancreatic adenocarcinoma." (PMID 34199169, 2021). "miR-302b exhibited anti-tumor activity by reversing EphA2 regulation, which relayed a signalling transduction cascade that attenuated the functions of N-cadherin, β-catenin, and Snail (markers of Wnt/β-catenin and epithelial-mesenchymal transition, EMT)." (PMID 35052421, 2021). "EphA2 has also been reported to compensate for the loss of EGFR signaling due to chemotherapy and thus maintain tumor progression." (PMID 35096972, 2021). "For example, data show that EPHA2 is overexpressed in BrCa clinical samples; however, there is also evidence that EPHA2 acts as a tumor suppressor in breast carcinogenesis." (PMID 33977106, 2021). "Next, to determine how oHSV EphA2 expression improved antitumor response, tumor growth studies were performed." (PMID 34599026, 2021). "The overexpression of EphA2 in tumours is related to tumour metastasis and poor prognosis of patients, which is caused by epithelial‐mesenchymal transition (EMT) of tumour cells." (PMID 33586348, 2021).
tumor (continued). "Using a modified indirect coculture model, we investigated the ability of tumor cell EphA2 to induce osteoclast differentiation of progenitor cells." (PMID 33869989, 2021). "Subsequently, the correlation between EphA2 and these 31 TFs was analyzed using the mRNA expression database of tumor cells in the TCGA database." (PMID 33712565, 2021). "The humanized EphA2 mAb 1C1, libelled with 64Cu, was used for positron emission tomography (PET) imaging of eight tumor models with different EphA2 expression levels, showing good correlation between tumor uptake and EphA2 expression." (PMID 34926242, 2021). "Consistently, cells cultured from EphA2-knockout KPC tumours (KPC-PDAC cells) display profoundly reduced ability to invade into Matrigel towards a gradient of HGF." (PMID 34819513, 2021). "This study suggested that EphA2, EphA3, EphA4, and EphA5 can act as tumor-inhibiting factors as well as biomarkers for the prognosis of BC." (PMID 34221956, 2021). "The western blot and immunohistochemistry analyses showed that EphA2 was also highly expressed in PDX tumor tissues at the protein level." (PMID 34831119, 2021). "We further report a non-canonical signaling function for ephrinA5 in HGSC cells, whereby, opposite to the tumor-suppressive signaling elicited by EphA2-ephrinA1 complexes, ephrinA5 even limits the canonical activation of EphA2 through phosphorylation at Y588." (PMID 33893375, 2021). "The inhibitory effect of anti-EphA2 on tumor cell killing was determined for KLE cells in the range 14%–40% (median 25%) and for RL95 cells in the range of 15%–40% (median 26%)." (PMID 34691070, 2021). "The role of EPHA/EFNA as tumor suppressors in breast carcinogenesis was also demonstrated by targeting EPHA2." (PMID 33977106, 2021). "EphA2 and EphA3 are commonly expressed in GBM, including in regions of tumor neovasculature, tumor-associated immune cells, and tumor-infiltrating cells, and associated with poorer outcomes in GBM patients." (PMID 34926242, 2021). "Multiple kinases are reported to control phosphorylation of EphA2 S897 in different tumor cell types at basal level and upon various treatments and among them RSK." (PMID 33671073, 2021). "We describe tumor context-specific examples of EphA2 signaling and the emerging role EphA2 plays in supporting cancer—stem—cell-like populations and overcoming therapy-induced stress." (PMID 33572284, 2021). "The combination of FAP+ CAF and EPH receptor A2 (EphA2)+ targeting resulted in complete tumor remission, which suggests a crucial supplemental role of CAF-targeting strategies along with conventional cancer therapies." (PMID 33806802, 2021). "This review summarizes the recent advances in understanding EphA2 function in cancer, with detail on the molecular determinants of the oncogene-tumor suppressor switch function of EphA2." (PMID 33572284, 2021). "In our study, we found that the expression level of EphA2 was reduced in BC, and up-regulation of EphA2 predicted better RFS, indicating that for this type of tumor, EphA2 can act as a tumor-inhibiting factor." (PMID 34221956, 2021). "In an intravenous (i.v.)A549 lung colonization model, i.v. co-injection of PBMCs with EphA2-TEA-VV one week after tumor challenge significantly delayed tumor progression compared to control virus and monotherapies." (PMID 33863363, 2021). "The EPHA2, ITGB4, and COL4A5 genes have been associated with tumor progression by exhibiting cell invasion and metastasis." (PMID 34299042, 2021). "In general, EPHA2 negatively regulates tumor growth and migration after canonical ligand-induced EPHA2 signaling, which inhibits the AKT-mTORC1 and MAPK pathways." (PMID 33977106, 2021). "Hsu and colleagues showed that EphA2-targeted CAR-T cells effectively killed EphA2-expressing OS tumor cells in pre-established, targeted xenografts in immunodeficient mice and were associated with prolonged survival." (PMID 34503279, 2021).
tumor (continued). "NOD SCID mice were inoculated with SiHa‐EphA2‐KD and SiHa‐Con cells and monitored the tumour development." (PMID 33586348, 2021). "Taken together, functional enrichment analysis of DEGs in each cell revealed that EphA2-SE plays a role in the development of tumor cells." (PMID 33712565, 2021). "Overexpression of EphA2 has been reported to inhibit cancer cell proliferation and motility, indicating that EphA2 can act as a tumor suppressor." (PMID 34221956, 2021). "The EphA2 S897 phosphorylation has earlier been reported to be controlled by RSK in tumor cells of different origins, including NSCLC." (PMID 33671073, 2021). "Moreover, no other EphA/EphB peptides were identified in the DNA-PKcs precipitates by LC-MS/MS analysis, suggesting a unique association of EphA2 with DNA-PKcs over the other Eph family members, albeit this may be related to tumor cell type and different EphA/EphB expression levels." (PMID 33671073, 2021). "Because of these excellent performances, MEDI-547 was expected to treat patients with insufficient expression of EphA2 in malignant tumor cells." (PMID 34202685, 2021). "EphA2 receptor has a pro-oncogenic property which activates the tumor-suppressive signaling pathways of EphA2, and inhibits the PI3K/Akt and ERK pathways." (PMID 34490085, 2021). "The effect of EphA2 on tumor resistance is also mediated by its physical and functional interaction with ErbB2/EGFR and the subsequent activation of signaling pathways that involve Ras/MAPK and RhoA." (PMID 33572284, 2021). "The humanized anti-EphA2 antibody DS-8895a was radiolabeled with [111In], [125I] and [89Zr], but because of its superior imaging and tumor uptake characteristics in breast cancer xenografts, [89Zr]Zr-DS-8895 was chosen as a lead compound." (PMID 34209513, 2021). "Further analyses revealed that blocking tumor EphA2 function reduced osteoclast precursor maturation into functional osteoclasts through an IL‐6–dependent mechanism in coculture." (PMID 33869989, 2021). "We found that the overexpression of EphA2 significantly increased cell proliferation, colony formation, cell migration and tumour sphere formation." (PMID 33586348, 2021). "Increasing evidence indicated that the EphA2 plays an important role in cell transformation, primary tumour progression, angiogenesis and metastasis in various tumour models." (PMID 33586348, 2021). "Elevated EphA2 expression positively correlated with poor prognosis, improved metastatic potential, and reduced overall survival of patients, in a tumor context-specific functioning." (PMID 33572284, 2021). "High levels of EphA2 expression are correlated with tumor grade, increased vascularization, and poor overall survival (OS) in RCC." (PMID 32814829, 2020). "Small animal imaging system and H&E staining showed that EphA2 knockdown decreased the liver metastasis of tumor cells." (PMID 32814829, 2020). "In summary, our data reveal that HDAC7 functions as an oncogene in NPC, and promotes the oncogenicity of NPC cells by inhibiting miR-4465 expression, and subsequently upregulating EphA2, and miR-4465 functions as a tumor suppressor in NPC." (PMID 32376822, 2020). "Antibody-dependent cell-mediated cytotoxicity (ADCC) can further promote anti-tumor activity of EphA2 mAbs." (PMID 32397088, 2020). "The tumor-selective EphA2 antibody EA2 was used in this way to direct unstimulated T cells to lyse EphA2-expressing tumor cells in vitro and in vivo." (PMID 32397088, 2020). "Agonist EphA2 mAbs caused proteasome-dependent degradation of the receptor, resulting in MHC class I presentation of EphA2 peptides on tumor cells and increased recognition by EphA2-specific CD8+ T cells in vitro." (PMID 32397088, 2020). "In all three models, EphA2-ILs-DTXp led to significant tumor regression that extended beyond the treatment period." (PMID 33092175, 2020).
tumor (continued). "EphA2-siRNA was incorporated into liposomal nanoparticles (DOPC) called EPHARNA (EphA2-siRNA-DOPC) specifically targeting EphA2 expression in the epithelial mediated tumor." (PMID 33003468, 2020). "Of interest, these tested EphA2-specifc T cells were shown to exhibit the ability to kill EphA2-positive tumor cells." (PMID 32811512, 2020). "MEDI-547 was shown to interact with EphA2 via the highly conserved extracellular domain with similar binding affinity observed for 1C1, with internalization in EphA2-expressing tumor cells and subsequent reduction of EphA2 protein levels." (PMID 32811512, 2020). "89Zr radiolabeling of the EphA2 mAbs 1C1, 3B10 and 2H7 was also used to compare their uptake as naked mAbs or as ADCs, in tumor cells and in vivo." (PMID 32397088, 2020). "This ligand- and tyrosine kinase-dependent EphA2 activation (reverse signaling) inhibits cancer cell proliferation, adhesion, and motility and tumor angiogenesis." (PMID 32848131, 2020). "In gallbladder carcinomas, upregulation of PI3K/MMPs/Ln-5γ2 and/or EphA2/FAK/paxillin contributed to tumor growth and VM formation." (PMID 32169087, 2020). "TMA staining results showed that both YB1 and EphA2 were upregulated in ccRCC, and YB1 was positively correlated with EphA2 in tumor tissues (r = 0.3374, P = 0.0166)." (PMID 32814829, 2020). "While antibody alone was not sufficient to inhibit tumor growth, adoptive transfer of anti-EphA2 CD8+ T cells led to tumor eradication." (PMID 32397088, 2020). "EphA2 overexpression has also been recorded in tumor-initiating cells within the GBM microenvironment, which are known to drive therapy resistance." (PMID 32340173, 2020). "Together, these results suggest that liposomal encapsulation and EphA2 targeting affect exposure of the drug in tumor cells, leading to a pronounced and sustained in vivo activity." (PMID 33092175, 2020). "EphA2 overexpression has been observed in tumor intestine compared to normal intestine, together with a change in the spatial expression of this receptor." (PMID 32316101, 2020). "In the BL-0293 and BL-0382 tumor models, EphA2-ILs-DTXp induced durable complete regressions in most treated animals, while free docetaxel led to only partial tumor regressions." (PMID 33092175, 2020). "EphA2 is a member of the EphA family of receptor tyrosine kinases (RTKs) and possesses both tumor-promoting role in a ligand-independent manner and tumor -suppressing role in a ligand-dependent manner." (PMID 32848131, 2020). "For instance, the tumor suppressive factor Slit2 can directly be downregulated by TEC via their receptor EphA2 in a paracrine manner." (PMID 32974337, 2020). "Our in vitro findings were reproduced on nude mice where shDNMT3B slowed down tumor growth, while miR-451a inhibitor partially restored the tumorigenicity of T24 cells with the involvement of EPHA2/PI3K/AKT axis." (PMID 33087088, 2020). "In all three tested models, the combination of EphA2-ILs-DTXp and gemcitabine led to significant tumor responses that extended beyond the treatment period." (PMID 33092175, 2020). "Together, our data suggest that miR-1224-5p downregulation is a frequent alteration in ESCC that promotes cell proliferation, migration, invasion and tumour growth by activating the EGFR-EFNA1/EPHA2-VEGFA signalling pathway via inhibition of TNS4 expression." (PMID 32732965, 2020). "IHC and haematoxylin and eosin (H&E) staining of subcutaneous tumor tissues demonstrated that EphA2 knockdown obviously decreased Ki-67 expression and tumor cell volume." (PMID 32814829, 2020). "The immunohistochemical assessment of key marker proteins in the tumor sections of each group revealed a significant reduction in EphA2 expression and activity in the presence of prazosin." (PMID 32203105, 2020). "Trivalent CAR T cells, targeting HER2, IL13-Rα2, and EphA2, exhibited excellent anti-tumor activity in vitro in the GBM model." (PMID 33224149, 2020).
tumor (continued). "In our experiments, the inhibition of EphA2 function impaired tumor cell growth and motility and, most importantly, reversed the drug resistance of HuH-7R cells." (PMID 32203105, 2020). "In the nude mouse model administered ovarian tumors intraperitoneally, EPHARNA was shown to be taken up by the tumor, reducing EphA2 levels in the animals 48 h following single treatment." (PMID 32811512, 2020). "Overexpression and aggressive features of EphA2 in tumor cells and relatively low expression in most normal adult tissues make this protein a potential therapeutic target in cancer." (PMID 32811512, 2020). "VE-cadherin regulates EphA2 activity, and EphA2 modulates the p85 regulatory subunit of PI3K, promoting the loss of tumor intercellular adhesion and facilitating cell migration and infiltration to form VM channels." (PMID 32116702, 2020). "MC-CAR T cells proved the most efficacious against 2 EphA2-positive tumor cell lines, expanding more and retaining their cytolytic capacity significantly longer than CD28 or 41BB." (PMID 33148882, 2020). "Preclinical studies suggest that EphA2-targeting contributes to EphA2-ILs-DTXp activity primarily through a shift in the microdistribution of the drug, resulting in increased tumor area drug exposure." (PMID 33092175, 2020). "The large extracellular domain of EphA2 provides an antigen that is frequently upregulated on tumor cells." (PMID 32811512, 2020). "Tumor proliferation (Ki-67) and apoptosis (cleaved caspase-3) were markedly altered under the combination of EphA2 targeting with sorafenib treatment." (PMID 32203105, 2020). "A series of assays validated that overexpression of EPHA2 rescued the tumor suppressive role of miR-451a in BCa cells." (PMID 33087088, 2020). "Initial studies identified anti-EphA2 mAbs with preferential binding to tumor cells that inhibited transformed or metastatic cell behavior in vitro, and inhibited tumor growth in mice, with anti-vascular effects." (PMID 32397088, 2020). "The ADC, generated by MedImmune and known as MEDI-547, effectively killed EphA2+ cells in vitro via caspase-mediated cell death, and more effectively inhibited tumor growth in mouse xenograft models, compared to naked 1C1." (PMID 32397088, 2020). "The BL-0440 tumor model was more resistant and led to partial regressions for both EphA2-ILs-DTXp and free docetaxel." (PMID 33092175, 2020). "The Ser897 phosphorylation of EphA2 by Akt is proposed to participate in tumor cell migration, invasion, and drug resistance." (PMID 32203105, 2020). "We also demonstrate in mouse models, that agonistic EphA2 targeting agents are very effective in suppressing cell migration and tumor metastases, hence anticipating the possible use of such agents in innovative anti-metastatic therapeutic modalities." (PMID 33023262, 2020). "In this assay, the cytotoxicity of T cells in freshly isolated cells from TET tissue was analyzed in a co-culture with tumor cells expressing EphA2 (U251) and EphA2/CD3-specific BiTE." (PMID 32132638, 2020). "The tumor‐suppressive EphA2‐pY588 was increased in OVCAR3 and to a less extent in OVCAR4, but was low in OVCAR8 with and without cisplatin." (PMID 32115889, 2020). "We found, however, that the effective RSKi treatments were tightly coupled with the induction of tumor‐suppressive EphA2‐pY588." (PMID 32115889, 2020). "The combination of EphA2-ILs-DTXp at 59 mg/kg and gemcitabine led to durable and complete tumor regressions in all animals." (PMID 33092175, 2020). "The EphA2-binding arm is designed to target the extracellular domain of EphA2, enhancing retention and delivery in the tumor." (PMID 33092175, 2020). "EphA2 mAb-conjugated liposomes (MM-310) bearing a hydrolytically sensitive docetaxel prodrug have shown promising anti-tumor activity in a range of xenograft models, with improved tumor penetration and anti-tumor activity compared to free docetaxel." (PMID 32397088, 2020).